IL5 (interleukin 5)
Diseases named in the same sentence as IL5 in open-access papers (continued):
Sharing a sentence is not in itself a finding about the gene and the disease.
asthma (continued). "Notably, a single dose of IL-5-anchored CCAR-T cells resulted in persistent protection against asthma-related conditions over three months, significantly exceeding the typical therapeutic window of current mAb-based treatments in the clinics." (PMID 35973984, 2022). "In T2 asthma, the Th2 cytokines IL-4, IL-5, IL-9, IL-13, and IL-25, and the acute proinflammatory cytokines TNF-α, IL-1β, IL-6, and IL-8, subsequently lead to bronchial hyperresponsiveness (BHR), and plasma cells and antibody-producing cells secrete antibodies." (PMID 36430662, 2022). "Moreover, it was disclosed that activation by IL-5 and GM-CSF was more pronounced for the eosinophils of asthma patients than for the control HS." (PMID 36497064, 2022). "A mouse asthma model was given oral/pulmonary administration of AG nanoformulation, and the bioavailability of the drug was greatly enhanced, as was the release of inflammatory factors (such as IL-4, IL-5 and IL-13), which were also significantly reduced." (PMID 35455087, 2022). "Th2-asthma (i.e., eosinophilic asthma) is well established to play a leading role in asthma development as more than half of asthma cases have a Th2 phenotype, characterized by the secretion of high levels of IL-4, IL-5, and IL-13 by Th2 cells." (PMID 35769905, 2022). "However, as our animals have been exposed to radon inhalation therapy, it is also of note that IL-5, alongside with IL-4, is also known to be involved in airway inflammation and hyperreactivity especially in asthma." (PMID 35203348, 2022). "The different mechanisms of action for anti‐IL5‐pathway treatments may explain such a different impact on the relevant component of T2 inflammation in severe asthma." (PMID 35423001, 2022). "Current immunomodulatory treatments for asthma mainly target mechanisms of type 2-related eosinophilic inflammation, such as corticosteroids and antibodies to target specific cytokine mediators (e.g., IL-5)." (PMID 36231116, 2022). "Benralizumab is another IL-5 inhibitor used in asthma with therapeutic prospects in BP." (PMID 36359364, 2022). "Similarly, in mice with OVA-induced asthma, significantly increased IL-5 (p < 0.01, 67.5 ± 20.40 pg/mL) and IL-13 (p < 0.01, 99.8 ± 22.99 pg/mL) levels were observed in BALF." (PMID 35631208, 2022). "Given the importance of local airway eosinophilopoiesis in severe asthma, local concentrations in the airways may be particularly important for optimal effect of anti-IL5 biologics." (PMID 36237537, 2022). "Targeted therapies directed against IL-5 and IL-5R for severe eosinophilic asthma have proved effective mainly in reducing asthma exacerbations and the use of daily oral corticosteroids but also in improving asthma control and lung function." (PMID 33921360, 2021). "A previous study showed that in utero exposures of C57BL/6 mice to 50mg/m3 of cigarette smoke led to exacerbated HDM-induced asthma in terms of increases in airway resistance, eosinophilic inflammation, and Il-4, Il-5, and IgE levels when compared to filtered-air controls." (PMID 34912233, 2021). "In fact, the overall importance of IL-5 and eosinophils in asthma was brought into question." (PMID 35126131, 2021). "Hence, we believe that ICS and eosinophilic targeted therapy (such as IL-5 antibody) are beneficial for the distinct disease subset with bronchiectasis-asthma-CRS overlapping in the same airway." (PMID 34225679, 2021). "Early experience with anti-IL-5 therapies demonstrated that they were effective in dramatically reducing the number of eosinophils in blood and sputum in asthmatics, but were ineffective in improving asthma outcomes." (PMID 34739571, 2021). "There are currently three FDA-approved anti-IL-5 therapies for asthma in the USA." (PMID 34739571, 2021). "Steroid-sparing anti-interleukin-5 (IL-5) agents and dupilumab should be considered as alternative treatment options for patients, such as ours, with eosinophilic, prednisone-dependent asthma refractory to omalizumab therapy." (PMID 34055544, 2021).
asthma (continued). "The therapeutic interventions for different phenotypes include IL-17 antagonist (neutrophilic asthma), IL-4/13 antagonist and anti-IgE (allergen-induced asthma), corticosteroids and IL-5 antagonist (idiopathic eosinophilic asthma), and leukotriene antagonist (aspirin exacerbated asthma)." (PMID 33505494, 2021). "Similarly, the prednisolone positive control group also showed reduced levels of IL-4, IL-5, and IL-10 compared to the asthma group." (PMID 33919400, 2021). "Th17- and Th2-mediated inflammatory pathways are regulated reciprocally during asthma, thus, inhibition of type 2 cytokines, such as IL-4 or IL-5, or administration of corticosteroids leads to reorganization of immune response from Th2-mediated eosinophilic to Th17-mediated neutrophilic disease." (PMID 34084159, 2021). "It is located on chromosome 5q31 within the T helper 2 (Th2)-cytokine locus including IL-5, IL-4, IL-13, and it could contribute to tissue-specific Th2 inflammation in asthma and allergic diseases." (PMID 33925009, 2021). "The production and release of epithelial cytokines, including IL-33, IL-25, and TSLP, lead to the recruitment and activation of ILC2, which secretes mediators, such as IL-5 and IL-13, that augment allergic inflammation in the pathogenesis of virus-induced asthma exacerbation." (PMID 35008429, 2021). "Another study in a mouse model of allergic asthma reported that intranasal administration of probiotic Lactobacillus rhamnosus GG prevents the development of asthma due to decrease in bronchoalveolar lavage the eosinophils cells, lung IL-5 and 13 levels, and airway hyperreactivity." (PMID 34557509, 2021). "Moreover, Th2-specific cytokines levels, including IL-4, IL-5, and IL-10, were lower in P. cocos extract-administrated groups at all doses than those in the asthma control group." (PMID 33919400, 2021). "Incidentally, asthma is characterized by increased Th2 cytokine production; however, in this model, Th2 cytokines, including IL-4, IL-5, and IL-13, which were upregulated in the HDM group, were not further upregulated in the HDM/RSV group at the mRNA and protein level." (PMID 34703996, 2021). "T2 high asthma is identified by high counts of airway eosinophil that can function as immunomodulator cells through the generation of a wide variety of cytokines, including IL-5." (PMID 34572281, 2021). "However, it was subsequently appreciated that benefit in patient populations correlated closely with the degree of eosinophilia and several studies have now conclusively validated the role of anti-IL-5 therapy in asthma." (PMID 34739571, 2021). "A possible explanation for the lacking in the reduction of eosinophils during OMA therapy in our patients could lie in the fact that actually the dominant pathway of their asthma endotype was that of IL-5." (PMID 33750842, 2021). "The most common asthma subtype is characterized by the involvement of T helper type 2 cells (Th2) sensitized primarily to allergens and subsequent eosinophilic airway inflammation triggered by the type two cytokines (particularly Il-5)." (PMID 34142656, 2021). "Although recent studies of anti-IL-5 therapies have led to a reduction in exacerbations and improvement of several asthma-control measures in a subpopulation of patients displaying severe eosinophilic asthma, there are other approaches for regulating eosinophils." (PMID 33917396, 2021). "In a murine model of asthma, miR-221 and miR-485-5p regulate interleukin-5 (IL-5) by targeting sprouty-related protein with an EVH1 domain-2 (Spred-2), which negatively regulates the Ras/ERK pathway involved in a variety of cellular processes, including airway inflammation and hypersensitivity." (PMID 34819948, 2021). "Notably, a manifestation of disease symptoms considered extensively as hallmarks of asthma is directly or indirectly related to the overproduction of IL-4, IL-5, and IL-13." (PMID 33649900, 2021).
asthma (continued). "In 2000, Graham14 and others proposed for the first time that children with bronchiolitis are prone to develop asthma, which may be related to the hyper-function of Th2-derived cytokines (interleukin-4 (IL-4), IL-5, and IL-13)." (PMID 33514798, 2021). "We found that treatment with anti‐IgE, anti‐IL‐5/R and anti‐IL‐4R while improving asthma outcomes, also all significantly reduced the symptoms of CRSwNP measured by SNOT‐20, supporting the “one airway concept” that assumes similar pathomechanisms in CRSwNP and asthma." (PMID 34331521, 2021). "However, more studies are needed to relate these changes to any clinical improvement observed after 8 weeks of treatment with an anti-IL-5 drug in patients with severe asthma." (PMID 33808110, 2021). "However, the role of IL-5 in asthma has been under scrutiny as studies have demonstrated that only 50% of asthma cases can be attributable to “allergic asthma”." (PMID 35387066, 2021). "In addition, both ALOX5 and IL5RA have been identified as susceptibility genes associated with asthma and asthmatic inflammation in humans, and a monoclonal antibody to the IL5RA ligand, IL5, is FDA-approved for the treatment of severe eosinophilic asthma." (PMID 35169481, 2021). "The numbers of both blood ILC2s and bronchoalveolar lavage fluid (BALF) ILC2s were shown to be increased in asthmatic mice, which contributed to the development of experimental asthma via the rapid secretion of IL-5 and IL-13 to aggravate lung eosinophilia and mucus production and exacerbate AHR." (PMID 34177881, 2021). "In asthma, after activation by epithelial-derived alarm cytokines, ILC2s promote pulmonary inflammation by secreting type 2 cytokines, including IL-4, IL-5, and IL-13, to enhance the contraction of smooth muscle, secretion of mucus, and infiltration of inflammatory cells." (PMID 34177881, 2021). "Interleukin-4 (IL-4), IL-13, and IL-5 are type 2 (Th2) cytokines that support the vital role of Th2 lymphocytes in asthma pathogenesis by reducing the release of immunoglobulin (Ig)E and eosinophil infiltration into lung tissues, which accelerate the process of allergic asthma." (PMID 34258300, 2021). "However, a comparative analysis of IL-5 and IL-13 production in murine experimental asthma showed that major producers of these type 2 cytokines are ILC2s, rather than Th2 cells." (PMID 34194431, 2021). "Administration of anti-IL-25 and anti-TSLP antibodies during ovalbumin-induced asthma could reduce the infiltration of inflammatory cells into airways, as well as local expression of IL-4, IL-5 and IL-13." (PMID 34084159, 2021). "Our results suggested that DCT might be beneficial to asthma airway inflammation through the suppression of IL-5 and IL-13 production." (PMID 34595240, 2021). "Inactive RA patients with concomitant asthma developed a flare of disease after anti-IL-5 monoclonal antibody treatment, which might be explained reasonably by the depletion of rEos." (PMID 34733292, 2021). "Similarly, anti-IL-5 therapy showed a more remarkable improvement of pre-bronchodilator FEV1 in asthma patients than in eosinophilic COPD." (PMID 34795588, 2021). "However, several studies have described the biomarkers for eosinophilic severe asthma, with peripheral eosinophils being considered the best predictor biomarkers for anti-IL-5 and anti-IL-5Rα therapies." (PMID 33525548, 2021). "Suppression of Notch1 expression by HAT inhibitors reduced Th2 cytokines, especially IL-4, IL-5, and IL-13, and it may provide a therapeutic alternative for asthma." (PMID 34566492, 2021). "Measurement of gene expression of the most important cytokines that drive T2-inflammation, specifically IL-4, IL-5, and Il-13, in induced sputum could be applied as a reliable biomarker for the identification of T2-high asthma." (PMID 33513844, 2021).
asthma (continued). "Therefore, dupilumab is the first biologic approved and specifically indicated for the treatment of uncontrolled severe asthma with Type 2 inflammation: asthma that includes allergic (anti-IgE) and/or eosinophilic (anti-IL5) phenotypes." (PMID 34020658, 2021). "Moreover, it is noteworthy that IL-9 which is a Type II cytokine behaved differently from other Type II cytokines (IL-4, IL-5, and IL-13) and was associated with an increase in ACE2 expression in sputum of asthma patients." (PMID 35111161, 2021). "Curcumin downregulated IL-4 and IL-5 levels but upregulated IFN-γ in the BALF of a murine model of asthma and attenuated allergic airway inflammation by modifying the balance of CD4‏+ CD25+ regulatory T cells (Tregs)/T-helper (Th) in ovalbumin (OVA)-sensitized mice dose-dependently." (PMID 34804178, 2021). "Moreover, we found the concentrations of IL-4, IL-5, and IL-13 were increased 4.71-fold, 3.58-fold and 3.42-fold in serum samples of asthma patients compared to healthy controls, respectively." (PMID 34749662, 2021). "In patients with severe asthma, there is strong association, measured by Spearman rank correlation, between BAL IL‐13 and IL‐ 4 concentrations, r = 0.749, p < 0.001 but weaker association between BAL IL‐13 and IL‐5 concentrations, 0.410, p < 0001." (PMID 33411348, 2021). "Interleukin (IL)-4, IL-13, IL-5, and Th2 cytokines have a significant role in asthma development." (PMID 35046828, 2021). "The mechanism was suspected to be that Th2 responses (including IL-4 and IL-5) and non-Th2 responses (IL-17), which were involved in the pathogenesis of asthma, might be protective against atherosclerosis and myocardial infarction." (PMID 34321496, 2021). "Furthermore, new and emerging biologic therapies for severe asthma are cytokine-based (anti-IL-4, IL-5, or IL-13) and mostly target Th2-mediated pathways." (PMID 33574813, 2020). "In particular, therapeutic strategies that could ensure an optimal engagement of PD-1 on ILC2s would directly reduce asthma pathogenesis, notably IL-5-mediated eosinophil recruitment and IL-13-dependent mucus metaplasia in the respiratory tract." (PMID 32778730, 2020). "After stopping anti-IL-5 treatment, eosinophils and asthma symptoms again increased." (PMID 33297418, 2020). "Anti-IL-5 (mepolizumab) was approved in late 2014 and receiving patients had decreased eosinophilic inflammation, reduced asthma exacerbations, improved asthma control markers, better quality of life, and reduced levels of some of the proteins that drive airway remodeling." (PMID 33297418, 2020). "Treatments for asthma that modulate eosinophil action are available; Reslizumab and Mepolizumab are anti-IL-5 antibody therapies that may have potential in treatment of viral respiratory disease, if eosinophils are activated." (PMID 32746922, 2020). "Exposure to rOPN could induce the expression of Tgfβ1 and the release of TGF-β1, IL-5, IL-13, and phosphorylated Smad3 in a mouse model of virus-induced asthma exacerbation." (PMID 32009132, 2020). "Therefore, the researchers concluded that ILC2s contributed to allergic airway inflammation in asthma by producing IL-5 and IL-13 to the same extent as Th2 cells." (PMID 32397396, 2020). "The cytokines of IL-4, IL-5, and IL-13 produced by Th2 cells are deeply involved in IgE synthesis, eosinophil activation, mucus secretion, and airway remodeling during the pathogenesis of asthma." (PMID 33192556, 2020). "Indeed, the Th2 cytokines IL-4 and IL-5 are not only critical for both IgE and eosinophil production, but also for the induction of the overall asthma phenotype and severity." (PMID 33101014, 2020). "The total annual exacerbation events (defined as the sum of courses of oral corticosteroid and antibiotics, sick leaves, hospitalisations and emergency room visits because of asthma during the last 12 months) were significantly reduced in the anti-IL5/IL5R group from 7.6/year to 3.2/year (p < 0.05)." (PMID 32467765, 2020).
asthma (continued). "The anti-IL5 antibody mepolizumab was approved in 2015 and since then has become an established therapy for patients with severe uncontrolled eosinophilic asthma Difficult-to-treat and severe asthma in adolescent and adult patients." (PMID 32093447, 2020). "MK2 and 3 are kinases activated by p38α; MK2/3 inhibitors or knockout of MK2/3 in mice reduced the production of IL-6 and IL-13 (two cytokines implicated in asthma) but not IL-5, IL-9 or GM-CSF in response to IL-33." (PMID 32103032, 2020). "Antigen-specific Th2 cells and their cytokines (such as IL-4Ra, IL-5, and IL-13), and inflammatory cells such eosinophils and mast cells are primary mediators of the pathological changes seen in asthma such as airway inflammation and airway hyper-responsiveness (AHR)." (PMID 33101014, 2020). "Furthermore, in patients with T2-high asthma IL-5 stimulates the interaction of eosinophils with periostin, an extracellular matrix protein whose expression resulted to be up-regulated during eosinophil migration towards airways." (PMID 33329598, 2020). "Targeting IL-5-driven eosinophil differentiation locally within the lung maybe of relevance for optimal control of airway eosinophilia and asthma." (PMID 33292332, 2020). "IL-5 is a cytokine derived from a wide variety of stromal and immune/inflammatory cells, beside Th2 cells, known to be mainly involved in eosinophil proliferation, differentiation, and recruitment in allergic diseases and asthma." (PMID 33328996, 2020). "On the other hand, a poor response to β2–agonists in patients with severe asthma and eosinophilia might predict a better response to anti–IL-5 therapy." (PMID 32328116, 2020). "In this manuscript, we found that NFATc2 mRNA positively correlated with IL‐5 in asthma." (PMID 33079489, 2020). "Moreover, IL-5 exerts an inhibitory effect on eosinophil apoptosis, and the numbers of apoptotic eosinophils are negatively correlated with sputum IL-5 concentrations in stable asthma, as well as during disease exacerbations." (PMID 33329598, 2020). "This and the activation of congenital type 2 lymphoid cells (ILC2s) could explain why elevated T2 cytokines such as IL-4 and IL-5 are found in asthma in parallel to an increase in TNF-α." (PMID 33134805, 2020). "Subsequently, Th2 cells produce cytokines related to asthma, such as IL-5, IL-4 and IL-13." (PMID 32397396, 2020). "Therefore, bone marrow ILC2s, in addition to airway ILC2s, are a possible early source of IL-5 in allergic diseases including asthma." (PMID 32582171, 2020). "Also, the authors identified a potential target of both miRNAs, SPRED2, a negative regulator of different mechanisms in asthma such as airway inflammation and hyperresponsiveness, by modulating IL-5 signaling pathway." (PMID 33488613, 2020). "IL-5 is another Th2 cytokine that has a role in the progression of asthma because benralizumab, an anti-IL-5 receptor antibody, showed its efficacy in the treatment of asthma." (PMID 32617136, 2020). "By targeting this axis, eosinophil levels and other inflammatory responses could potentially be reduced for individuals with still unmet clinical needs despite anti-IL-5 and other asthma therapies." (PMID 32466530, 2020). "Indeed, if the development of new therapies in asthma remains essential, the last years have seen the emergence of biotherapies efficiently targeting the Th2 pathway (anti-IL5, anti-RIL-5) in severe asthma." (PMID 31996218, 2020). "However, more recently, elevated sputum IL-5 and submucosal and sputum eosinophils have been reported in obese patients with asthma." (PMID 31362741, 2019). "Treatment with drugs that inhibit IL-5 improve quality of life and asthma symptoms." (PMID 30630412, 2019). "Therefore, to evaluate the anti-IL-5 effect of MSCs in children with asthma under different conditions, we divided them into subgroups." (PMID 31673233, 2019).